FOXM1 (forkhead box M1)
Diseases named in the same sentence as FOXM1 in open-access papers (continued):
Sharing a sentence is not in itself a finding about the gene and the disease.
invasive breast carcinoma (5 papers, 2008 to 2021). A carcinoma that infiltrates the breast parenchyma. "hsa-miR-671-5p is a tumor-suppressor miRNA that is significantly decreased in invasive breast cancer by the deregulation of FOXM1, promoting cell invasion." (PMID 30884856, 2019). "In invasive breast carcinomas (ductal type) FOXM1 expression was often abundant in the nucleus (IRS = 3) as well as in the cytoplasm (IRS = 12) compared with normal breast tissue and ductal carcinoma in situ." (PMID 18254960, 2008). "Using immunohistochemistry (IHC) we systematically analysed FOXM1 expression in human invasive breast carcinomas (n = 204) and normal breast tissues (n = 46) on a tissue microarray." (PMID 18254960, 2008). "FOXM1 expression was positively correlated with PARP1 expression in breast-invasive carcinoma." (PMID 34880209, 2021). "Furthermore, FOXM1 was found to be overexpressed during progression from DCIS to invasive breast cancer." (PMID 21314937, 2011). "After bioinformatics analysis, we found that the expression levels of FOXM1 and PARP1 were higher in breast invasive carcinoma tissue than in adjacent tissue." (PMID 34880209, 2021).
liver fibrosis (5 papers, 2020 to 2026). "In the CCl4‐induced liver fibrosis model, hepatocyte deletion of Chrebpα led to a further increase of both E2f1 and Foxm1 mRNA levels in the liver of CCl4‐injected mice." (PMID 40548862, 2025). "The activation of FOXM1 as well as the AKT/PI3K signaling pathway has been reported to aid in driving hepatic stellate cell activation as well as liver fibrosis." (PMID 34447693, 2021). "The molecules, including Scd1, Acta2, collagen type I alpha 1 chain (Col1a1), Timp1, Foxm1, Sult1e1, and plasminogen activator (Plat), are also involved in hepatotoxicity pathways, such as liver fibrosis, liver hyperplasia/hyperproliferation, liver proliferation, and liver necrosis/cell death." (PMID 34539442, 2021). "In mouse model, FoxM1 drives inflammation responses for liver fibrosis and hepatocarcinogenesis." (PMID 32471201, 2020).
lung adenoma (5 papers, 2009 to 2024). A benign, well circumscribed epithelial neoplasm that arises from the bronchus or the lung parenchyma. "FOXM1 was demonstrated to be necessary and sufficient to cause the progression of lung adenomas into invasive mucinous adenocarcinomas in vivo by activating AGR2." (PMID 36304306, 2022). "FOXM1 caused progression of lung adenomas into invasive, metastatic adenocarcinomas with a mucinous phenotype." (PMID 29267283, 2017). "In summary, activation of FOXM1 in pre-existed lung adenomas caused progression to invasive, metastatic adenocarcinomas." (PMID 29267283, 2017). "Previous studies with Mx-Cre Foxm1fl/fl mice demonstrated that deletion of Foxm1 from all cell types of the body caused a significant reduction in number and size of lung adenomas induced by urethane." (PMID 19672312, 2009). "Deletion of Foxm1 from epithelial cells caused a striking decrease in the number and size of lung adenomas." (PMID 19672312, 2009). "Low-grade lung adenomas were present 14 weeks after initiation of urethane, at which time epiFoxM1-ΔN mice were treated with Dox to express the FoxM1-ΔN transgene in SP-C-expressing cells and lung epithelial cells." (PMID 29267283, 2017). "In the present study, expression of FoxM1-ΔN in urethane-induced lung adenomas decreased NKX2.1 and increased tumor progression and mucin production." (PMID 29267283, 2017). "Expression of FOXM1 in Rosa26-FoxM1 transgenic mice accelerated proliferation of tumor cells and increased the number and size of lung adenomas after tumor initiation/ promotion with 3-methylcholanthrene (MCA)/butylated hydroxytoluene (BHT)." (PMID 29267283, 2017). "Taken together, our data demonstrate that FOXM1 expression in lung tumors suppresses NKX2.1 and causes progression of lung adenomas into poorly differentiated, mucinous, metastatic lung adenocarcinomas." (PMID 29267283, 2017). "FOXM1 induced progression of lung adenomas into invasive, metastatic adenocarcinomas with a mucinous phenotype." (PMID 29267283, 2017). "Thus, expression of activated FoxM1-ΔN in lung adenomas increased tumor cell proliferation and induced SOX2." (PMID 29267283, 2017). "Although our previous studies emphasized the essential role of Foxm1 in lung tumorigenesis, its specific role in lung epithelial cells, the precursors of lung adenoma or adenocarcinoma cells, was not addressed." (PMID 19672312, 2009).
osteoarthritis (5 papers, 2019 to 2024). A noninflammatory degenerative joint disease occurring chiefly in older persons, characterized by degeneration of the articular cartilage, hypertrophy of bone at the margins and changes in the synovial membrane. "For example, miR-877-5p can affect cellular activities by regulating the transcription of forkhead box M1 (FOXM1) in osteoarthritis models." (PMID 34654353, 2021). "Studies have indicated the involvement of the FoxO family and FoxM1 in the development of osteoarthritis." (PMID 35153742, 2021). "Knockdown/silencing of FoxM1 inhibited the production of inflammatory factors and NF-κB activation, enhancing cell viability in an osteoarthritis model." (PMID 35153742, 2021). "The knockdown of FOXM1 reduces the inflammatory response induced by osteoarthritis." (PMID 37238726, 2023). "FoxM1 impairs chondrocyte viability and accelerates the development of osteoarthritis." (PMID 35153742, 2021).
renal fibrosis (5 papers, 2021 to 2024). A final common manifestation of a wide variety of chronic kidney diseases characterized by glomerulosclerosis and tubulointerstitial fibrosis. "The increase in FoxM1 under pathological condition is implicated in renal fibrosis via up‐regulating multi‐Wnts expression in epithelial cells, then promoting the activation of β‐catenin signalling pathway." (PMID 33434361, 2021). "FOXM1 activates the β‐catenin pathway and contributes to renal fibrosis by regulating members of the multi‐Wnt family." (PMID 38063438, 2024). "Since then additional studies have been published describing a role for Foxm1 in renal fibrosis, diabetic nephropathy, and polycystic kidney disease." (PMID 38916959, 2024). "In conclusion, our data demonstrated that up‐regulated transcriptional factor FoxM1 stimulates multi‐Wnts transcription and then promotes renal fibrosis via activating Wnt/β‐catenin signalling pathway." (PMID 33434361, 2021). "In unilateral ureteral obstruction (UUO)‐induced renal fibrosis mice, our preliminary study result showed that FoxM1 was persistently increased in the fibrotic kidneys." (PMID 33434361, 2021). "Compared with MCD, FoxM1 was remarkably increased in biopsy samples of MN, IgAN and DN patients with renal fibrosis." (PMID 33434361, 2021). "Pharmacological inhibition of FoxM1 expression significantly attenuated the progression of renal fibrosis." (PMID 33434361, 2021). "The results in the study suggest that FoxM1 is a pivotal regulator in promoting renal fibrosis, but what is line on the upstream of FoxM1 still need to be elucidated." (PMID 33434361, 2021). "The elevation of FoxM1 was also observed in FA‐induced renal fibrosis animals." (PMID 33434361, 2021). "The preliminary observation on biopsies from patients with renal fibrosis suggested that the expression of FoxM1 was increased in different renal fibrosis and mainly located in renal tubular epithelial cells, which strengthened the clinical relevance of the study." (PMID 33434361, 2021). "The up‐regulation of FoxM1 was also observed in biopsy samples with renal fibrosis." (PMID 33434361, 2021). "We next sought to assess whether the lack of tubular Foxm1 and associated reduced proximal tubule proliferation might exacerbate the delayed development of renal fibrosis after AKI, the so-called AKI to CKD transition." (PMID 38916959, 2024). "FOXM1 may exhibit a significant switch in activating the β-catenin pathway and renal fibrosis." (PMID 37238726, 2023). "FoxM1 might be a key switch for activating β‐catenin pathway and renal fibrosis." (PMID 33434361, 2021). "Therefore, FOXM1 may be a critical factor in the control of renal fibrosis." (PMID 37238726, 2023). "Therefore, FoxM1 might be a potential therapeutic target in manipulating renal fibrosis." (PMID 33434361, 2021). "Pharmacological inhibition of FoxM1 down‐regulated multi‐Wnts elevation in UUO mice and attenuated renal fibrosis." (PMID 33434361, 2021).
rheumatoid arthritis (5 papers, 2020 to 2023). A chronic, systemic autoimmune disorder characterized by inflammation in the synovial membranes and articular surfaces. "Furthermore, the FOXM1 inhibitor thiomycin inhibits the production of human osteoclasts and forms a target for the potential treatment of rheumatoid arthritis." (PMID 37238726, 2023). "FOXM1 inhibitor inhibited osteoclastogenesis, indicating that it may be a potential target for the treatment of rheumatoid arthritis." (PMID 33633721, 2020). "In addition to the FoxO family, FoxM1, which is related to damage to subchondral bone, may also play a role in the pathogenesis of rheumatoid arthritis." (PMID 35153742, 2021). "Thus, thiostrepton, a direct inhibitor of FoxM1, which inhibits FoxM1 binding to genomic target sites, may be a new approach to rheumatoid arthritis treatment." (PMID 35153742, 2021). "In addition, FOXM1/LINC00152 feedback loop regulates the proliferation and apoptosis in rheumatoid arthritis fibroblast-like synoviocytes via Wnt/β-catenin signaling pathway." (PMID 33072778, 2020).
soft tissue sarcoma (5 papers, 2009 to 2025). A malignant neoplasm arising from muscle tissue, adipose tissue, blood vessels, fibrous tissue, or other supportive tissues excluding the bones. "Well-differentiated liposarcomas and myxoid liposarcomas arise from a common first order branch but are separate from other FOXM1 candidate soft tissue sarcomas." (PMID 27074562, 2016). "We measured Foxm1 gene expression in murine soft tissue sarcomas and found a correlation with the development of lung metastases (p = 0.01)." (PMID 19956606, 2009). "Inhibition of FOXM1 in soft tissue sarcomas has been shown to reduce tumor size in vivo, suggesting that targeting FOXM1 may offer a viable therapeutic strategy for CC." (PMID 41256331, 2025). "This postulate is partly substantiated by recent experimental evidence in which deregulated Hippo pathway signaling in soft-tissue sarcomas was found to promote FOXM1 expression and tumorigenesis in undifferentiated pleomorphic sarcoma, fibrosarcoma and liposarcoma." (PMID 27074562, 2016). "We next analyzed the expression of FOXM1 in a clinically annotated tissue microarray (TMA) containing 166 MFH samples and 48 other soft tissue sarcomas." (PMID 19956606, 2009).
Arthritis (4 papers, 2020 to 2023). Inflammation of a joint. "Recently, arthritis-associated precursor macrophages (AToMs) containing osteoclast precursors were identified, and the differentiation of AToMs from osteoclasts was regulated by FOXM1." (PMID 33633721, 2020). "In the arthritis model of Foxm1 global knock-out mice (Foxm1flx/flxRosa26CreERT2), articular bone erosion was partially alleviated and the joint swelling was alleviated." (PMID 35650653, 2022). "Unlike osteoclasts in physiological bone metabolism, differentiation into osteoclasts is regulated by the transcription factor forkhead box protein (Fox) m1 and is hampered by Foxm1 inhibitors in arthritis." (PMID 35270012, 2022). "The absence of FOXM1 inhibits the ability of arthritis-associated osteoclastogenic macrophages (AtoMs) to become osteoblasts in vitro and in vivo." (PMID 37238726, 2023). "In arthritis, FOXM1 regulation may inhibit inflammatory responses and joint destruction, reduce pain, and improve joint function." (PMID 37238726, 2023). "In addition, the FoxM1 inhibitor thiostrepton significantly suppressed bone destruction in arthritis and differentiation into osteoclasts." (PMID 35650653, 2022).
bronchopulmonary dysplasia (4 papers, 2019 to 2023). Bronchopulmonary dysplasia is a chronic respiratory disease that results from complications related to lung injury during the treatment of infant acute respiratory distress syndrome in low-birth-weight premature infants or from abnormal lung development in older infants. "FOXM1 is a key mediator in lung development and the treatment of bronchopulmonary dysplasia (BPD)." (PMID 37238726, 2023).
cervical squamous cell carcinoma (4 papers, 2017 to 2025). A squamous cell carcinoma arising from the cervical epithelium. "This positive feedback was then further verified using rescue assays, which indicated that indeed SIRT7 promoted the autophagy and inhibited ROS production through USP39 and FOXM1 in cervical squamous cell carcinoma." (PMID 37957720, 2023). "According to the GEPIA analysis, the expression of USP39 and FOXM1 was in positive correlation in the cervical squamous cell carcinoma (R = 0.36, p-value = 1e-10)." (PMID 37957720, 2023). "Moreover, SIRT7 expression was revealed to be downregulated after USP39 silencing, which was reversed after FOXM1 overexpression in cervical squamous cell carcinoma cells." (PMID 37957720, 2023). "SIRT7 promoter region was found to be bind with FOXM1 in cervical squamous cell carcinoma cells." (PMID 37957720, 2023). "SIRT7/USP39/FOXM1 is highly expressed in CSCC, but whether the pathogenesis in cervical squamous cell carcinoma patients is inhibited by acetylation of USP39 at the k428 site still needs further study." (PMID 37957720, 2023). "Finally, we wanted to explore whether SIRT7 regulates oxidative stress in cervical squamous cell carcinoma via USP39 and FOXM1." (PMID 37957720, 2023).
colorectal tumors (4 papers, 2015 to 2019). "In our present study, we detected the expression of FOXM1 in colorectal tumor tissue specimens by immunohistochemical staining from 87 CRC patients and investigated the relationships among mediated gene knockdown of FOXM1 on SW620 cells and EMT, proliferation, migration and invasion in vitro." (PMID 25935853, 2015). "Our results also highlight the importance of the EGFR-Ras-FOXM1-β-catenin signaling axis in CRC and indicate that the expression of the transcription factor FOXM1 in colorectal tumors may be a potential predictive marker of response to cetuximab therapy in this disease." (PMID 28423516, 2017). "Therefore, we decided to analyze whether expression of FOXM1 and/or b-catenin in human colorectal tumors may constitute a predictive factor of response to anti-EGFR therapy." (PMID 28423516, 2017). "To investigate whether FoxM1 is highly expressed in CRC tissues, we first detected the expression of FoxM1 protein in the 87 primary colorectal tumors and paired adjacent normal colorectal tissue specimens as well as invasive lymph nodes using immunohistochemical staining." (PMID 25935853, 2015). "Our immunostaining results showed a FoxM1-positive staining in the nucleus and/or cytoplasm of colorectal tumor cells and invasive lymph nodes, whereas there was negative or weakly positive staining of FoxM1 in the paired adjacent normal colorectal tissues." (PMID 25935853, 2015).
Fanconi anemia (4 papers, 2017 to 2021). Fanconi anemia (FA) is a hereditary DNA repair disorder characterized by progressive pancytopenia with bone marrow failure, variable congenital malformations and predisposition to develop hematological or solid tumors. "Additionally, we measured the homologous recombination repair (HRR) activity to determine whether the HRR involved in the last step of the Fanconi anemia pathway was regulated by the inhibition of FOXM1 expression." (PMID 32486251, 2020). "The study also showed that FOXM1 can increase anticancer drug resistance by regulating the expression of FANCD2, which regulates the Fanconi anemia pathway and consequently increases DNA repair." (PMID 32486251, 2020). "Investigation have shown that FOXM1 directly regulated the transcription of FANCD2, which is the key gene of the Fanconi anemia (FA) pathway." (PMID 32486251, 2020). "For example, a module composed of a FoxM1 transcription factor network, an E2F transcription factor network, Aurora B kinase signaling, ATR signaling, PLK1 signaling, and members of the Fanconi anemia DNA damage response pathway was densely connected." (PMID 29988723, 2018).
heart failure (4 papers, 2020 to 2025). Inability of the heart to pump blood at an adequate rate to meet tissue metabolic requirements. "In conclusion, in the human hypertrophied heart, the BRG1/FOXM1 complex plays a vital role in the prevention/treatment of heart failure by regulating the angiotensin-converting enzyme/angiotensin-converting enzyme ratio." (PMID 37238726, 2023). "When FOXM1 was removed from mice, the young mice died of heart failure shortly after birth." (PMID 37238726, 2023).
kidney cancer (4 papers, 2016 to 2023). Primary or metastatic malignant neoplasm involving the kidney. "As expected, FOXM1 protein level was decreased in kidney cancer cells transfected with siMELK, probably due to the decrease of FOXM1 transcription." (PMID 26933922, 2016). "We also demonstrated that the combination of OTS514 and OTS167 can effectively reduce the expression levels of TOPK, MELK and FOXM1, and decreased viability of kidney cancer cells." (PMID 26933922, 2016). "In summary, we suggest that both TOPK and MELK are attractive molecular targets for kidney cancer treatment and they constitute a feedback loop with an oncogenic transcriptional factor FOXM1." (PMID 26933922, 2016). "FOXM1 is overexpressed in various human malignancies, including prostate, breast, lung, colon, stomach, liver, and kidney cancer, via the activation of Ras and cyclin D1 and FOXM1-depletion is sufficient to decrease carcinogenesis by stimulating apoptosis 45-47." (PMID 37908734, 2023). "Collectively, our assays implied that both inhibitors are very effective to suppress kidney cancer cell growth through reduction of TOPK, MELK, and FOXM1 proteins that may cooperatively constitute a critical signal pathway in kidney cancer cells." (PMID 26933922, 2016). "In fact, FOXM1 is overexpressed in various human malignancies, including prostate, breast, lung, ovary, colon, pancreas, stomach, bladder, liver and kidney cancer, and its oncogenic activity is downstream of Ras and cyclin D1, which are often implicated in epithelial tumors." (PMID 27385468, 2016). "We then exogenously introduced FOXM1 expression vector into two kidney cancer cell lines and found the significant elevation of TOPK and MELK mRNA expression in the cells transfected with FOXM1 expression vectors, while no change was observed in those transfected with the mock control vector." (PMID 26933922, 2016). "Taken together, these results suggest that FOXM1 may function as a transcriptional factor that induces expression of TOPK and MELK genes in kidney cancer cells." (PMID 26933922, 2016). "Similarly, our results in kidney cancer cells treated with the IC50 concentration of MELK inhibitor (OTS167) showed decrease of MELK and TOPK proteins as well as FOXM1 protein." (PMID 26933922, 2016).
liver disease (4 papers, 2021 to 2026). "Interestingly, of liver disease-related 5 DE genes between Phb1+/− and WT, the mRNA expressions of forkhead box M1 (Foxm1) and TIMP inhibitor of metalloproteinase (Timp1) were matched with validation for RNA-seq in liver tissues and AML12 cells transfected with Phb1 siRNA." (PMID 34539442, 2021).